CD4 (CD4 molecule)
Diseases named in the same sentence as CD4 in open-access papers (continued):
Sharing a sentence is not in itself a finding about the gene and the disease.
sarcoidosis (continued). "The Kaiser study found that co-expression of RORγt and T-bet in CD4+ cells was higher in the BAL of patients with Löfgren syndrome as compared to non-Löfgren sarcoidosis, suggesting that co-expression predicted a more favorable phenotype." (PMID 32774332, 2020). "Despite the frequent use of the CD4/CD8 ratio for the diagnosis of sarcoidosis, this ratio does not reflect the severity of the disease." (PMID 32760396, 2020). "There are also no mycobacterial-specific CD4+ T cell clones identified from sarcoidosis patients to date." (PMID 32256501, 2020). "CD4+ T cells with a Th17 phenotype and T cells expressing both IL-17 and IFN-γ (i.e., Th17.1 cells) have been found in lung tissue and BAL from patients with sarcoidosis." (PMID 32256501, 2020). "From a register consisting of 749 sarcoidosis patients [Löfgren’s syndrome (LS) n = 274, non-LS n = 475] with information on Vα2.3+ T-cells, an expansion of CD4+ Vα2.3+ T-cells (CD4+ Vα2.3+ T cells > 10.5% in BALF) was seen in 268 (36%)." (PMID 32111204, 2020). "High level of CD4+/PD1+ lymphocytes, reduced cytokine secretion, dysfunctional proliferation, and increased apoptosis were also observed among sarcoidosis patents, but blocking PD-1 pathway in CD4+ T cells could reverse the proliferative capacity." (PMID 30069490, 2018). "Although CD4-positive T-lymphocytes are thought to play an important role in sarcoidosis, its pathogenesis has not been fully elucidated, although the excessive activation of CD4 positive T lymphocytes is a hallmark of sarcoidosis." (PMID 30452447, 2018). "Our study showed that the CD4/CD8 ratio in lymph node samples was significantly different by chest radiographic stage, suggesting that the lymphocyte profile is related to the pathology and prognosis of sarcoidosis." (PMID 30452447, 2018). "Finally, examination of PD-1 expression in matching sarcoidosis BAL and PBMC demonstrated significantly more PD-1+CD4+ cells in BAL than in PBMC, in which on average 25.1% versus 8.4% PD-1+CD4+ cells are present, respectively (p < 0.05)." (PMID 29234685, 2017). "In CD4+ group 44 VJ combinations pairs expressed higher usage and 2 VJ combination pairs showed lower usage than CD8+ group, while 101 VJ pairs showed higher usage and 1 VJ pair showed lower usage in CD4+ group than in sarcoidosis tissue group." (PMID 29163767, 2017). "The functional delineation of Foxp3+CD4+T cells into rTregs and mTregs based on CD45RA and FoxP3 expression had lead to the observations that mTregs were main suppressors in chronic inflammatory disease, sarcoidosis, liver cirrhosis and cancer." (PMID 29127350, 2017). "Additionally, RNA-sequencing of specific T-cells, such as CD4+ and CD8+, and perhaps other T-cell subpopulations such as regulatory T-cells (Treg), would be beneficial for identifying expressed genes in sarcoidosis phenotypes." (PMID 28717140, 2017). "Moreover, in contrast to CD4, the percentage of CD8 lymphocytes was lower in the sarcoidosis VLF samples, to a similar degree as the elevation in BALF samples." (PMID 27930546, 2016). "Also sarcoidosis CD3+, CD4+ and CD8+ PBTLs displayed lower mean fluorescence intensity of AUF1 (p≤0.02) and HuR (p≤0.03) proteins than control healthy PBTLs." (PMID 27575817, 2016). "Serum soluble interleukin-2 receptor (sIL2R) and serum Krebs von den Lungen-6 (KL6) values are correlated with the number of total cells, lymphocytes and T-lymphocytes bearing CD4 in BALF, suggesting that these may reflect alveolitis induced by sarcoidosis." (PMID 26271927, 2015). "The aim of the study was to investigate the fractions of FoxP3+ CD4+ T cells, Th1, Th17, and IFN-γ+ Th17 cells in BALF and to assess the hypothesis about an imbalance between these subsets in sarcoidosis." (PMID 24882950, 2014). "Comparing the number of T cell expansions, the difference in frequency of CD4+ TCR Vβ T cell expansions in lung vs. blood of sarcoidosis patients (p = 0.56) or controls (p = 0.12) was not statistically significant." (PMID 24656074, 2014).
sarcoidosis (continued). "In addition to CD4+ T cells, CD8+ T cells have also been found in granulomas and BAF, while its role in the pathogenesis of sarcoidosis is unclear." (PMID 24885153, 2014). "The thorax computed tomography can reveal hilar lymphadenopathy presence; the high rates of CD4/CD8 in the bronchoscopy and in the BAL fluid may lead to a conclusion in favor of sarcoidosis." (PMID 24381778, 2013). "For example, the CD4/CD8 ratio in BALF is usually high in sarcoidosis, but is not increased in peripheral blood." (PMID 23497225, 2013). "Preliminary ex vivo studies that employed flow cytometry to investigate peripheral blood lymphocytes in sarcoidosis patients demonstrated a greater activation of nonstimulated CD4+ and CD8+ BALF T cells compared to peripheral blood lymphocytes." (PMID 26464848, 2013). "In the sarcoidosis patients, the Th17 cell population in BALF (3.05% ± 1.87%) was increased compared with levels in PBMCs (1.61% ± 1.09%) (p < 0.05), while CD4+ CD25high Foxp3+ Tregs in BALF were increased (2.19% ± 1.71%) compared to levels in PBMCs (0.95% ± 0.91%) (p < 0.05)." (PMID 24177566, 2013). "BAL lymphocytosis, high CD4/CD8 ratio, and elevated serum ACE levels in this group may be considered as important laboratory markers for the diagnosis of sarcoidosis." (PMID 23521826, 2013). "Specific cutaneous lesions along with BAL lymphocytosis, high CD4/CD8 ratio and elevated serum ACE levels may be predictors of progressive disease in sarcoidosis." (PMID 23521826, 2013). "Compared with conventional CD4+ T cell lines that were co-cultured with anti-CD3 and anti-CD28 antibodies, polarized Th17 cells from both a BD patient, a sarcoidosis patient, and a healthy donor produced large amounts of IL-17, particularly BD T cells, as determined by ELISA." (PMID 22546542, 2012). "Other investigations such as BAL documenting a lymphocytic alveolitis with increased CD4/CD8 ratio, and elevated serum angiotensin-converting enzyme may provide additional evidence of sarcoidosis." (PMID 20727133, 2010). "Sarcoidosis is a systemic inflammatory disease characterized by noncaseating granulomas which consist of CD4+ T-cells and macrophages surrounded by CD8+ T-cells." (PMID 20140091, 2010). "Non-treated patients with sarcoidosis-related symptoms had significantly higher lymphocytosis and CD4/CD8 ratios as well as total BALF cell count and giant cells in BALF, compared with asymptomatic patients." (PMID 19242869, 2009). "The positive correlation between the CD4+ IFN-γ producing T cells in BALF and in induced sputum, suggest that sarcoidosis patients could be followed up with this noninvasive method which has to be investigated in further studies." (PMID 15978129, 2005). "Therefore, the aim of this study was to explore induced sputum (IS) CD4+ Th1 T-lymphocyte subpopulation and to compare them with those in the BALF in patients with sarcoidosis." (PMID 15978129, 2005). "The authors showed for the first time a significantly higher percentage of IFN-γ producing CD4+ T cells together with a markedly increased ratio of IFN-γ/IL-4-producing CD4+ T cells in BALF, after PMA/ ionomycin stimulation in patients with sarcoidosis compared with normal subjects." (PMID 15978129, 2005). "Additionally, the role of the CD4/CD8 T-lymphocyte ratio in BAL remains controversial, although some studies suggest that ratios greater than 3.5 have a specificity greater than 95% for the diagnosis of sarcoidosis." (PMID 39867510, 2025). "Finally, flow cytometric analysis of BALF leukocytes can easily be combined with flow cytometric analyses of lymphocyte surface markers, which is used for specific indications (eg, analysis of the expression of the T cell markers CD4 and CD8 in patients with suspected sarcoidosis." (PMID 38548099, 2024).
sarcoidosis (continued). "We found that of all indices tested, two immune blood T lymphocytes markers (CD4+CD31+ and CD4+CD44+), two BALF T lymphocytes markers (CD8+CD31+ and CD8+CD103+) and one chest CT sign (a number of lung nodules) are potential prognostic factors for the course of sarcoidosis." (PMID 37239108, 2023). "Furthermore, it was found that ‘naïve’ CD4+ T cells from patients with sarcoidosis were enriched for markers of non-TCR-mediated activation, apoptosis, and differentiation dysregulation." (PMID 37189479, 2023). "Sarcoidosis is a multisystem non-caseating granulomatous disease of unknownorigin characterized by T-lymphocyte activation and accumulation of CD4-positiveT-lymphocytes in the organs involved, most commonly the lungs." (PMID 38152007, 2023). "Normal CD4/CD8 ratio values do not exclude sarcoidosis, as the disease may be inactive at the time of examination." (PMID 36672683, 2023). "The blood CD4+CD31+ T lymphocyte and CD4+CD44+ T lymphocyte counts, the BAL fluid CD8+CD31+ T lymphocyte and CD8+ CD103+ T lymphocyte counts, and the number of lung nodules on chest CT may be reasonable predictors of sarcoidosis progression." (PMID 37239108, 2023). "Concordance between imputed and clinical total monocyte (22/30) and imputed and clinical CD4+ T-cell (26/30) grouping was established and provides additional evidence to support the utilization of in-silico deconvolution to determine PBMC cell proportions in sarcoidosis." (PMID 36311769, 2022). "In our sarcoidosis patients, double positive CD4+CD103+ cells were more elevated in peripheral blood than in the alveolar compartment, suggesting that the lower expression of CD103 on CD4 BAL lymphocytes may be related to their peripheral origin." (PMID 35629428, 2022). "A study reported several markers that may play a key role in the pathogenesis of sarcoidosis, most prominently, increased expression of regulatory receptors CTLA-4 and PD-1, as well as inducible co-stimulator (ICOS) in the CD4+ T-cell population in patients with nodular LS." (PMID 35615369, 2022). "Shorter duration could be explained by the absence of severe quantitative CD4 count defect, the rarer use of immunosuppressive drugs, and the lower proportion of blood positive antigen testing in patients with sarcoidosis than in other patients." (PMID 35425769, 2022). "In addition, we also demonstrated that the AUROC of the fractions of lymphocytes with small and round nuclei was comparable to that of the BALF CD4/CD8 ratio, which is widely used clinically to support the differential diagnosis between sarcoidosis and other ILDs." (PMID 34217348, 2021). "However, a CD4/CD8 ratio > 3.5 has a specificity of 93–96%, although with a sensitivity of 53 to 59% and a CD4/CD8 ratio > 10 has a >99% specificity for a diagnosis of sarcoidosis." (PMID 34573900, 2021). "However, BAL lymphocytosis is not specific for sarcoidosis and the importance of the CD4/CD8 ratio is controversial unless it is greater than 3.5, showing a specificity of 93 to 96%." (PMID 33807303, 2021). "Since that initial study, a large amount of evidence has emerged, such as elevations of CD4/CD8 lymphocyte ratios in bronchoalveolar lavage fluid seen in both CD and sarcoidosis, as well as similar signs of response to mycobacterial infection in CD18 and sarcoidosis tissues." (PMID 33319056, 2020). "CD4/CD8 ratio measurements are available in 38 of our sarcoidosis patients but not all of them." (PMID 33062080, 2020). "While healthy subjects’ CD4+CD25high cells accelerated granuloma formation, no changes in the time course of granuloma growth were observed with sarcoidosis patient cells, indicating a defect in the suppressive function of Tregs in sarcoidosis." (PMID 32751786, 2020).
sarcoidosis (continued). "In contrast, additional phenotyping of CD4+CD45RA- memory T cells demonstrated an expansion of CXCR5-expressing T follicular helper (TFH)-like cells with a significant increase of CXCR3-expressing TFH1-like cells and a decrease of CCR6-expressing TFH17-like cells when compared to sarcoidosis." (PMID 33613543, 2020). "The proportion of Tfh cells (CD4+CXCR5+PD1+) which are closely correlated with the differentiation and maturation of B cells increased significantly in the peripheral blood of patients with active sarcoidosis as compared to patients with stable sarcoidosis and healthy controls." (PMID 32508842, 2020). "In sarcoidosis, fluorescence measurement further revealed compartment-specific differences of TIGIT, but not of PD-1 expression; TIGIT levels were significantly higher in T cells (including CD4+, CD8+, and FOXP3+) in the intergranulomatous area as compared to the granulomas (p < 0.05)." (PMID 30733837, 2019). "Nonetheless, these criteria may be too restrictive: it has been shown that a typical presentation on chest CT-scan, and hyperlymphocytosis with a CD4/CD8 ratio greater than 3.5 on broncho-alveolar lavage, combined with the exclusion of other possible diagnosis, are highly predictive of sarcoidosis." (PMID 29641520, 2018). "The immunophenotype of sarcoidosis CD4+ T cells was examined, conducting analysis of spontaneous and TCR-stimulated cytokine expression, proliferation, apoptosis, and PD-1 expression for each sarcoidosis subject until the limit of PBMC availability was reached." (PMID 29234685, 2017). "Sarcoidosis is an inflammatory disease of unknown etiology driven by T-cell mechanisms, particularly by accumulation of activated CD4 T-cells in the lungs and by the formation of noncaseating epithelioid cell granulomas." (PMID 28717140, 2017). "Non-treated patients with sarcoidosis-related symptoms had significantly higher lymphocytosis (45±19% versus 39±17%, P<0.01), CD4/CD8 ratio (9.3±5.0 versus 5.7±4.5, P<0.001), and total BALF cell count (411±322 106/mL versus 334±273 106/mL, P<0.05), compared with asymptomatic patients." (PMID 19242869, 2009). "Although recent meta-analysis has shown that elevated CD4/CD8 ratio lacks sufficient specificity (0.83) and sensitivity (0.70) to diagnose sarcoidosis, BAL CD4/CD8 analysis may still prove helpful in gauging likelihood of sarcoidosis versus other ILDs when combined with other measurements." (PMID 33036432, 2020). "Thus, T cell exhaustion is not a terminal fate in sarcoidosis CD4+ T cells." (PMID 29234685, 2017). "However, it is not clear whether the Th17/Treg balance is affected in CD4+ T-cell mediated sarcoidosis." (PMID 24177566, 2013). "Importantly, TNFα is an essential target for treatment and we found that mo-DCs from patients with sarcoidosis, not influenced by the micro-environment of the lung, induced increased TNFα release upon interaction with naïve CD4+ T cells when compared to controls." (PMID 22513006, 2012). "Unlike sarcoidosis, active TU is characterised by marked CXCR5 down‐regulation on B cells and CD4+ T cells that normalises on remission." (PMID 40469525, 2025). "During resolution of sarcoidosis, PD1+CD4+ T cells in peripheral blood (PB) decreased and normalization of immune function was observed, indicating that the phenotypical and functional T cell changes can be reversible." (PMID 38715030, 2024). "CXCR5 was upregulated in sarcoidosis Tregs and CD8+ cells, but CD4+CXCR5+ T follicular helper cell numbers were not affected." (PMID 38173720, 2023). "A much larger study of 102 sarcoidosis patients showed progressively increased levels of CCL-18 and CCL-17 (a CD4 T-cell chemoattractant), but not TNF-α, in BAL of Scadding stage 1–4 patients (n=32/35/23/12, respectively)." (PMID 36543347, 2022). "Comparison of the immune cell compartments to sarcoidosis patients without PML revealed an increase in Treg frequencies and a concomitant decrease of CD4+ T cell numbers." (PMID 34993476, 2022).
sarcoidosis (continued). "An increased cellular count with a lymphocytosis > 25% and an elevated CD4/CD8 ratio are common findings, though they are neither sensitive nor specific for a diagnosis of sarcoidosis." (PMID 34573900, 2021). "We sequenced CD4+ cell group (n = 7), CD8+ cell group (n = 7) and lung sarcoidosis tissue group (n = 6, one patient failed to provide tissue), all sequences were aligned to TCR references from IMGT database and deeply analyzed for further study." (PMID 29163767, 2017). "Second, patient A’s bronchial CD4/CD8 ratio was <3.5, a finding with a negative predictive value of 85 % for the diagnosis of sarcoidosis." (PMID 26001889, 2015). "Although not statistically significant, BAL lymphocytosis, particularly with a high CD4/CD8 ratio, and an elevated serum ACE, were highly suggestive of sarcoidosis in the context of nonspecific cutaneous involvement with no other systemic findings." (PMID 23521826, 2013). "In Sarcoidosis 8, activation with ESAT-6, katG, Ag85A, and sodA resulted in moderate proliferation of the CD4+ and CD8+ T cells compared to no peptide or KLH (neoantigen), while heat shock protein elicited low level proliferation." (PMID 21092305, 2010). "As it has already been reported, the mean CD4+/CD8+ ratio was not significantly different between BALF and induced sputum in 20 sarcoidosis patients (p > 0.253) and in normal controls (p > 0.3)." (PMID 15978129, 2005). "CINS symptoms, biological, and CSF features were similar between CINS patients with and without sarcoidosis except regarding CD4 cells percentages and CD4/CD8 ratio that was higher in those with sarcoidosis (47 ± 12 vs. 22 ± 18, p = 0.02 and 2.24 ± 1.42 vs. 0.83 ± 1.10, p = 0.03, respectively)." (PMID 35425769, 2022). "Regarding cellular immunity, CD4 cells proportion among total lymphocyte blood count and CD4/CD8 ratio were higher in CINS patients with sarcoidosis than in those without sarcoidosis (47 ± 12 vs. 22 ± 18, p = 0.02 and 2.24 ± 1.42 vs. 0.83 ± 1.10, p = 0.03, respectively)." (PMID 35425769, 2022). "DCs isolated from BAL from sarcoidosis patients did not induce enhanced T cell proliferation, a skewed T cell differentiation or significant differences in the induction of several cytokines in a MLR with allogeneic naïve CD4+ T cells, compared to controls." (PMID 22513006, 2012). "On the other hand, both serum ACE levels and BAL CD4 and CD8 cell numbers were not indicative of sarcoidosis, and the tuberculin test created a dilemma as to whether we should start glucocorticoids in our patient, since the acid-bacilli cultures were pending." (PMID 18605996, 2008). "A proportion of CD4+ Vα2.3+ T-cells in BALF > 10.5% was found to be highly specific for sarcoidosis, with a specificity of 97% but with a sensitivity of 36% (p < 0.0001), calculated on all 749 sarcoidosis patients, including LS as well as non-LS patients, and 108 controls." (PMID 32111204, 2020). "In addition, impaired thymic T-cell differentiation in sarcoidosis was also suggested by high expression of non-TCR-mediated cell activation markers in total peripheral blood “naive” Th cells, apoptosis-related proteins, and profoundly dysregulated CD4+ T-cell differentiation." (PMID 38179278, 2023).